MTOR (mechanistic target of rapamycin kinase)
Diseases named in the same sentence as MTOR in open-access papers (continued):
Sharing a sentence is not in itself a finding about the gene and the disease.
diabetes (continued). "mTOR is a protein kinase and acts as a central regulator of many fundamental cell processes from protein synthesis to autophagy and glucose homeostasis, while impaired mTOR signaling has been involved in the progression of pathological conditions such as cancer and diabetes as well as in aging." (PMID 35409380, 2022). "Altogether, these observations suggest that GLP-1 could activate the PI3K/Akt/mTOR/NF-κB P65 pathway and act as a bridge between diabetes and food allergy." (PMID 36496564, 2022). "Our findings suggest that the modulation of mTOR signaling could be a promising therapeutic strategy for PND in patients with diabetes." (PMID 34784444, 2022). "Thus, trehalose as an inducer of mTOR-independent autophagy is effective at alleviating neuronal and behavioral disturbances accompanying experimental diabetes." (PMID 34685538, 2021). "In a study of a rat model of STZ-induced mild diabetes, the heart of adult offspring showed a reduction in mTOR protein levels and in the phosphorylation of serum- and glucocorticoid-inducible kinase 1 (SGK1), a downstream target of the mTORC2 pathway, which phosphorylates FoxO1." (PMID 34803741, 2021). "The effects of mTOR on diabetes are complex, with the anti- and pro-diabetic effects." (PMID 33691762, 2021). "Two main mTOR inhibitors are sirolimus (rapamycin) and everolimus that have substantial inhibitory effects on the mTOR signaling pathway that may be beneficial in reducing diabetes complications." (PMID 35178356, 2021). "Hence, trehalose as an inducer of mTOR-independent autophagy seems to be a promising agent for the treatment of neuronal and behavioral disturbances accompanying experimental diabetes." (PMID 34685538, 2021). "mTOR activation in diabetes may be responsible for the accumulation of excess iron seen in this illness; alternatively, accumulation of iron might activate mTOR, leading to diabetes." (PMID 34613935, 2021). "Indeed, metformin, an FDA approved diabetes drug that modulates mTOR/AMPK has been investigated as a potential therapeutic to target deficits with T cell aging." (PMID 34367184, 2021). "Immunotherapies such as PD/PD-L and CTLA-4 inhibitors can reduce the production of insulin from islet cells as in type 1 diabetes mellitus, whereas targeted treatments such as PI3K/mTOR inhibitors can induce insulin resistance similar to that seen in type 2 diabetes mellitus." (PMID 34830886, 2021). "Translational control of HIF-1α via mTOR may be relevant in diabetes, as hyperinsulinemia inhibits mTOR signaling." (PMID 34426491, 2021). "Furthermore, mTOR and p70S6k phosphorylation were increased in the heart tissue of diabetes mellitus rats, which were inhibited by exenatide treatment." (PMID 31199578, 2020). "In order to determine the underlying mechanisms by which BAI-LZM inhibits renal fibrosis and decreases inflammation, the protein expression levels of NF-κB, p-NF-κB p65, IL-1β, IL-6 and mTOR in diabetic kidney tissues were assessed using IF, IHC and western blot analyses." (PMID 32398108, 2020). "An animal study confirmed that streptozotocin-induced diabetes increases mTOR levels in rats." (PMID 32775437, 2020). "Our data indicated that the risk of diabetes varied with mTOR downstream target EIF-4E and EIF-4A, but not with RP-S6K or EIF4EBP2." (PMID 32978410, 2020). "Phosphatidylinositol 3-kinase/protein kinase B/mammalian target of rapamycin (PI3K/Akt/mTOR) signaling pathway regulates metabolism, proliferation, cell cycle, and protein expression, and its imbalance is involved in the development of obesity and diabetes." (PMID 32471207, 2020). "On other hand, berberine could ameliorate diabetes-associated cognitive decline and hepatic ischemia/reperfusion injury via down-regulating PI3K/Akt/mTOR signaling pathway." (PMID 33362566, 2020).
diabetes (continued). "In adipose tissues, autophagy was significantly increased in diabetes compared with non-diabetes, and mTOR expression was decreased in adipose of diabetes cases, indicating autophagy was negatively regulated by mTOR expression in adipose tissues of patients with diabetes." (PMID 32660483, 2020). "The efficacy of vitamin D3 against diabetes-associated cardiac hypertrophy is mediated by increased sirtuin-1, in association with attenuated DNA oxidative damage, decreased PARP1 and lower mammalian target of rapamycin (mTOR) phosphorylation." (PMID 31434333, 2019). "In diabetic animal models, the results concerning mTOR activity in the brain are not consistent, possibly caused by different durations or stages of diabetes." (PMID 30911292, 2019). "The mechanistic target of rapamycin (mTOR) is a key kinase linking diabetes and AD." (PMID 30684442, 2019). "On the contrary, other studies revealed that enhancing macrophage autophagy by the mTOR inhibitor may be a viable therapeutic or preventative approach to inflammatory disease, obesity insulin resistance, and diabetes." (PMID 31080547, 2019). "Dysregulation of mTOR occurs in diabetes, cancer and neurological disease." (PMID 29424687, 2018). "Dysregulation of mTOR under pathological and diseases states such as obesity, diabetes and cancer, could have adverse effects on the circadian clock and circadian behavioral and physiological processes." (PMID 29750810, 2018). "IGF1R and mTOR inhibitors might interfere with glucose metabolism and iatrogenic diabetes has been reported as side effect of IGF1R inhibitors." (PMID 29486734, 2018). "Problems with the mTOR pathway contribute to several diseases including diabetes and cancer." (PMID 29424687, 2018). "However, aberrant regulation of mTOR is known to play a significant role in various maladies including cancer, diabetes, aging, and cardiovascular diseases." (PMID 30305865, 2018). "Among women with diabetes, insulin use (n = 53) was significantly associated with higher tumor protein expression of IGF1R (OR = 2.36; 95%CI:1.02–5.52; p = 0.04) and p-mTOR (OR = 2.35; 95%CI:1.13–4.88; p = 0.02), especially among women treated with insulin analogues." (PMID 29486734, 2018). "Furthermore, MTOR has been demonstrated to be involved in the onset and progression of autoimmune disorders including diabetes." (PMID 30469437, 2018). "This suggests that DT may have a bioactive potency similar to IGF-1, which increases protein synthesis in diabetes to restore muscle wasting through the activation of Akt/mTOR pathways." (PMID 29181401, 2017). "mTOR responds to numerous stresses, while its dysregulation could result in cancer, metabolic disease and diabetes." (PMID 28402274, 2017). "This implies that, in diabetes setting, impaired mTOR pathway and weakened productions of IL-15 and IGF-1, exhibit mutual effects and may reach a low-level equilibrium state, an important mechanism that causes dysfunction of DETC and defective wound repair." (PMID 29225596, 2017). "As a routine oral agent for T2DM, metformin might be a potential pharmacological therapeutic target to protect against MI/R injury under diabetes on the regulation of cardiac oxidative stress and mTOR signaling." (PMID 28298952, 2017). "In this review, we will focus on the role of oxidative stress and mTOR signaling in the pathophysiology of MI/R injury in diabetes and discuss potential mechanisms and their interactions in an effort to provide some evidence for cardiometabolic targeted therapies for ischemic heart disease (IHD)." (PMID 28298952, 2017). "AS-IV also attenuated the diabetes-related activation of Akt/mTOR, NFκB, and Erk1/2 signaling pathways without causing any detectable hepatotoxicity." (PMID 27585918, 2016). "The mammalian target of rapamycin (mTOR) is a key pathway in cell growth and homeostasis, and its deregulation is involved in many diseases including cancer, cardiovascular disease, and diabetes." (PMID 27070592, 2016).
diabetes (continued). "Furthermore, imbalances in the mTOR pathway are involved in cardiac hypertrophy, inflammatory diseases, and diabetes, and pharmacological intervention of mTOR has been proposed as a potential treatment for these conditions." (PMID 26622487, 2015). "In addition, the involvement of an mTOR pathway in the aging process and pathological changes such as tumor formation, cancer, insulin resistance, and diabetes has been pointed out by many researches." (PMID 25364730, 2014). "Finally, more recent reports demonstrated that mTOR contributes to proximal tubular cell apoptosis and damage in diabetes." (PMID 25126552, 2014). "One trial (NCT01150097) currently underway is investigating the effects of everolimus with CNI elimination/reduction on renal function in de novo liver transplant recipients and will also provide more information on the role of mTOR inhibitors on posttransplant diabetes and hypertension." (PMID 24719752, 2014). "Therefore, great interest exists in the development of mTOR inhibitors as therapeutic drugs for obesity or diabetes." (PMID 24710396, 2014). "One well-tolerated agent that inhibits mTOR is metformin, widely used for diabetes management." (PMID 24216701, 2013). "Recent reports from our lab suggest that in the presence of diabetes mellitus, elevation of extracellular signal response kinase activity may promote decreased p27Kip1 mRNA and produce a relative resistance to mTOR inhibition." (PMID 24276258, 2013). "We hypothesized that addition of rapamycin, an mTOR inhibitor capable of inducing operational tolerance in allogeneic bone marrow transplantation, would result in improved diabetes reversal rates and overall glycemia." (PMID 23826229, 2013). "Starvation diabetes could be explained by deactivation of mTOR, which otherwise is activated by nutrients." (PMID 22683661, 2012). "Among signaling pathways activated in the kidney in diabetes, mTOR- (mammalian target of rapamycin-)regulated pathways are pivotal in orchestrating high glucose-induced production of ECM proteins leading to functional and structural changes in the kidney culminating in adverse outcomes." (PMID 22454628, 2012). "The same mTOR-centered point of view is applicable to the diabetes paradox." (PMID 22683661, 2012). "Moreover, distinct biological mechanisms, such as the unique effects of lipid metabolism dysregulation on cellular pathways like Akt and mTOR, may further explain why dyslipidemia differs mechanistically from diabetes, hypertension, and obesity." (PMID 41139205, 2025). "Our investigation shows the following: (a) Diabetes is associated with increase in the kidney expression of CLCA1 and TMEM16A, resulting in increased Cl– current; (b) CLCA1/TMEM16A/Cl– current system participates in stimulation of mTOR and increased matrix protein expression." (PMID 39782685, 2025). "In obesity, elevated BCAAs may arise from reduced skeletal muscle oxidation and incomplete catabolism, contributing to mTOR activation and insulin resistance; however, in overt diabetes, enhanced proteolysis and altered gut microbiota activity can accelerate their depletion." (PMID 41002949, 2025). "For example, a VEGF inhibitor may be most optimal agent to be administered to patients with uncontrolled diabetes mellitus or active lung disease, while an mTOR inhibitor could be the suitable choice in patients with uncontrolled arterial hypertension, cardiac history, or high risk of hemorrhage." (PMID 41303577, 2025). "Pancreas/duodenum homeobox protein 1 (Pdx1) and diabetes‐related genes are implicated in beta cell survival through direct regulation of ATF5, a downstream target of ATF4, modulated by eIF4E‐binding protein 1 (4ebp1) within the mammalian target of rapamycin (mTOR) pathway." (PMID 39668579, 2025). "Moreover, chronic activation of mTOR may also alter the metabolic and functional properties of specific immune cells, hence contributing to β-cell impairment and diabetes development." (PMID 39201476, 2024).
diabetes (continued). "Similarly, the study also found that the disorder of the mTOR signaling pathway may be related to the progress of cancer, diabetes, and aging process." (PMID 38338049, 2024). "However, overactivation of mTOR signaling might increase weight gain, diabetes, and other metabolic complications." (PMID 38365306, 2024). "These events may contribute to allograft failure (e.g., nephrotoxicity, hypertension) or increase the risk of cardiovascular disorders (e.g., dyslipidemia, hypertension, post-transplant diabetes mellitus), as well as drug discontinuation, as seen in mTOR inhibitor-induced mouth ulcers." (PMID 38138933, 2023). "Moreover, whether an mTOR-targeted agent adheres to a certain diabetes state needs to be elucidated to avoid misuse." (PMID 37298150, 2023). "Indeed, glucose uptake and thermogenesis in BAT upon β3‐adnergic stimulation that is supported by mTOR activity may be relevant to ameliorating obesity and diabetes." (PMID 36063136, 2022). "Following activation of mTOR, cells enter into a growth mode, in which mTORC1 and mTORC2 orchestrate a wide range of diverse functions during embryonic development, aging, and diseases (e.g. cancer, diabetes, neurodegenerative disorders) by initiating biosynthetic cascades." (PMID 35013125, 2022). "Finally, we discuss the promise of new therapies that address the underlying biology of bone aging, most notably through removal of senescent cells or modulating mTOR pathways, to improve bone health across the human life course and especially in people living with diabetes." (PMID 35388291, 2022). "With respect to the role of the hepatic mTOR pathway in the pathogenesis of olanzapine-associated disturbances of glucose and lipid metabolism, correcting the over-activation of mTOR signaling may hypothetically prevent weight gain, obesity, prediabetes, diabetes, and other metabolic complications." (PMID 35013125, 2022). "Hence while mTOR inhibition may improve bone health in older adults and those with disease conditions such as diabetes, use of this class of drugs in pediatric patients should be very carefully considered." (PMID 35388291, 2022). "Mechanisms underlying the role of BCAAs in AS may involve promotion of inflammation and OxS in endothelial cells, insulin signaling disruption, and chronic mTOR (mammalian target of rapamycin) activation that can lead to diabetes, which is a powerful determinant of vascular ageing." (PMID 35629874, 2022). "PI3K/Akt/mTOR pathway was significantly downregulated in the brain of streptozotocin-induced type 2 diabetic rats, this might explain the neurodegeneration commonly observed in diabetes." (PMID 35449001, 2022). "Interestingly, neither obesity nor diabetes were associated with higher or lower mTOR/pmTOR expression in our studies." (PMID 34066040, 2021). "Both pathways involve the mechanistic target of rapamycin (mTOR) to regulate a variety of components of the translational machinery in homeostasis, their dysregulation results in aberrant translation which is often detected in diabetes, neurological disorders, and cancer." (PMID 33672592, 2021). "However, the mTOR activation in immune cells may exacerbate β cell dysfunction, thus aggravating diabetes." (PMID 33691762, 2021). "HGF binds to c-Met in the plasma membrane, activates the AKT/mTOR signalling pathway, plays a vital role in cell growth, metabolism, cell survival and migration; in addition, HGF is closely associated with developmental defects, cancer, diabetes and autoimmune diseases." (PMID 32795289, 2020). "Second, we found that molecular activation of small intestinal mTOR blunts the glucose-lowering effect of the oral anti-diabetic agent metformin, while inhibiting small intestinal mTOR alone lowers plasma glucose levels by inhibiting glucose production in rodents with diabetes as well." (PMID 30755615, 2019).
diabetes (continued). "Furthermore, many other factors, such as the nutritional/metabolic status and endogenous insulin levels of the patients, which are interrelated with the severity of diabetes and diabetes treatment, might influence mTOR signaling." (PMID 29486734, 2018). "mTOR was already well known as a regulator of growth and protein translation, it is now clear that mTOR functions as a central coordinator of organismal metabolism in response to both environmental and hormonal signals, and it involved in the development of diabetes." (PMID 29802157, 2018). "This increased β-cell toxicity induced by the chronic mTOR inhibitor treatment might be a bridge leading to the development of new onset of diabetes mellitus after solid organ transplantations, imposing the need of the development of strategies to avoid this adverse effect." (PMID 30034573, 2018). "Consequently, we confirmed reduced activity of mTOR signaling components and higher expression of atrophy-related markers typified by FoxO1/atrogin-1/MuRF1 and myostatin-Smad2/3 signaling during the course of diabetes." (PMID 30510624, 2018). "PI3K/mTOR signalling is a key regulator of the major cellular processes such as cell proliferation and cell growth, and deregulation of this signalling pathway contributes to the pathogenesis of various diseases such as cancer, diabetes, obesity, hereditary diseases, and neurodegenerative disorders." (PMID 27036037, 2016). "This diabetes-mediated decrease in HIF-1α protein expression could stem from a defect in phosphorylated Akt (pAkt)-mTOR-dependent signaling because this pathway has been shown to stimulate HIF-1 translation in response to nutrient, growth factors and forskolin." (PMID 25381014, 2015). "However, further studies are warranted to clarify which ingredients of UP have those effects as well as to provide strong evidence of the functional roles of UP with Akt/mTOR pathways on hypothalamic ER stress-induced metabolic disease conditions such as obesity and diabetes mellitus." (PMID 26610463, 2015). "Because leucine regulates several cellular processes via mTOR and possibly through other signaling pathways, the likely beneficial effects of leucine supplementation have been evaluated in a variety of situations, including as a dietary supplement for the treatment of obesity and diabetes mellitus." (PMID 26007339, 2015). "However, hyperglycemia, rather than growth factors such as insulin, may contribute more to mTOR activation in diabetes because mTOR is activated even in the kidneys of insulin-independent type 1 diabetic models." (PMID 25126552, 2014). "Cardiac hypertrophy also may be a product of increased mTOR activity during diabetes." (PMID 22545721, 2012). "In addition, these same mTOR inhibitors may suppress premature aging and some are employed to treat diabetes and prevent/suppress obesity (metformin)." (PMID 21487160, 2011). "Indeed, mTOR hyperactivation may contribute to cancer growth, obesity, diabetes as well as premature aging." (PMID 21487160, 2011). "It is also involved in the treatment of metabolic diseases, such as diabetes, inflammation, and cancer, by modulating signaling pathways (NF-κB, PI3K/AKT/mTOR, RAS/RAF) and inflammatory markers (IL-6, IL-1β, TNF-α)." (PMID 42282446, 2026). "This study investigates the effects of maternal diabetes on hippocampal structure and autophagy‐related mechanisms in neonatal rats, focusing on the PI3K/mTOR signaling pathway." (PMID 40660790, 2025). "Recently, a huge number of molecular pathways have beenimplicated in the pathogenesis of diabetes mellitus type 2 (T2DM) & transition to a prediabetic state, among these pathways are insulin resistance, mammalian target of rapamycin (mTOR) and autophagy." (PMID 40533788, 2025). "The PI3K/AKT/mTOR, NF-κB, and MAPK signaling pathways, along with oxidative stress, play crucial roles in diabetes and its complications by regulating glucose metabolism and insulin sensitivity." (PMID 40871631, 2025).